TNF (tumor necrosis factor)
Diseases named in the same sentence as TNF in open-access papers (continued):
Sharing a sentence is not in itself a finding about the gene and the disease.
colitis (continued). "Exposure to IS also caused colitis in mice: it shortened colon and increased colonic myeloperoxidase, TNF-α, and IL-6 expression and NF-κB+CD11c+ cell (dendritic and macrophage cells) number, resulting in colonic inflammation." (PMID 36926604, 2023). "Excessive oxidative stress and abnormal production of proinflammatory cytokines are associated with colitis pathogenesis with the aberrant release of proinflammatory cytokines, including TNF-α, IFN-γ, IL-6, IL-8, IL-12, and IL-17." (PMID 36829894, 2023). "Infectious diseases related to the cause of colitis cytokine activate the protective response of immune cells such as macrophages, neutrophils, and lymphocytes in the colonic mucosa and induce TNF-α, IFN-γ, IL-6, and other immune cells." (PMID 37834221, 2023). "Conversely, prior ST7 infection exacerbated the severity of colitis by increasing the proportion of pathogenic bacteria and inducing pro-inflammatory IL-17A and TNF-α-producing CD4+ T cells." (PMID 36793854, 2023). "The induction of acute DSS colitis is characterized by extensive epithelial erosion, loss of goblet cells, leukocyte infiltration, and simultaneous increase in expression of the TNF-α and IFN-γ in colon tissues of diseased animals." (PMID 37532996, 2023). "Thiopurine and anti-TNF agents are associated with a decreased risk for CRC in patients with longstanding extensive colitis." (PMID 36831424, 2023). "Oral delivery of nanoparticles containing curcumin in dextran sulfate sodium (DSS)-induced colitis in Guinea pigs was associated with a substantial drop in tissue LPx and PC levels, leukocyte infiltration, and TNF-α production." (PMID 37701897, 2023). "The chronic TNBS-induced colitis model is associated with the significant production of pro-inflammatory cytokine TNF-α." (PMID 37760938, 2023). "G significantly ameliorated the extent of colitis, which was associated with a decrease in the expression levels of pro-inflammatory cytokines and chemokines, including interleukin IL-1β, IL-6, TNF-α, CXCL2, and CCL2 in the inflamed mucosa." (PMID 35456938, 2022). "We measured the levels of inflammatory cytokines such as IL-1β, TNF-α, IL-6, and IL-10, which are linked to colitis." (PMID 36456585, 2022). "ICI-associated colitis is routinely treated with immunosuppressive therapy, including corticosteroids and/or agents targeting tumor necrosis factor-α (TNF-α)." (PMID 35814408, 2022). "In support, glucosamine was able to reduce colitis-associated symptoms in DSS-treated mice by reducing TNF-α, IL-1β, and NF-kB expression in the colonic mucosa, and increasing the expression of ZO-1 and occludin tight junction proteins." (PMID 36009057, 2022). "In a colitis animal model induced by dextran sulfate sodium (DSS) and 2,4,6-trinitrobenzene sulfonic acid, maresin-1 suppressed disease activity in colitis and improved weight loss by decreasing IL-1β, TNF-α, IL-6, and IFN-γ in the acute phase." (PMID 35163291, 2022). "Both ponciretin and poncirin were shown to suppress NF-κB and TNF-α-linked inflammation and ameliorate colitis in a chemically induced mouse model, with ponciretin demonstrating superior anti-inflammatory properties." (PMID 35751094, 2022). "Colitis induction in untreated rats caused necrotic effects in colon tissues, a significant increase in colonic IL-1β, TNF-α, MPO, and MDA levels, and a remarkable decrease in GSH and TAC levels in colon tissue in comparison to the control group." (PMID 35428860, 2022). "As TNF, IL-6 is also involved in the inflammatory process related to colitis and is associated with the regulation of the adaptive immune response." (PMID 35295931, 2022). "Treatment with TNF-α antagonists Enbrel or Remicade ameliorates HIF-2α promoted colitis, which is a high-risk factor for CRC." (PMID 35954156, 2022).
colitis (continued). "In classical NEMO hypomorphism or IKK-β deficiency, TNF leads to increased cell death, disrupting barrier integrity and triggering inflammatory response pathways that result in clinical features, such as colitis, that accompany immunodeficiency." (PMID 35289316, 2022). "Enriched A. muciniphila eroded the mucus layer, impairing the intestinal barrier, which in turn posed greater susceptibility to colitis in mice, and induced excessive secretion of inflammatory cytokines (IL-1β, IL-6, and TNF-α)." (PMID 36312913, 2022). "Colitis was defined by assessing weight loss, colonic length, histological score, TNF-α levels, nitric oxide levels, cyclic adenosine monophosphate levels, MPO activity, and inducible nitric oxide synthase gene expression in colonic tissue." (PMID 35239781, 2022). "Impaired intestinal barrier integrity is another essential feature of colitis and is caused by aberrant IL-1β and TNF-α levels." (PMID 35126813, 2022). "Gene ontology analyses revealed 21 terms associated with the pathogenesis and progression of UC and colitis-associated carcinogenesis, including TNF-α signaling via NF-κB, G1 to S cell cycle control, Wnt signaling and apoptosis." (PMID 36361810, 2022). "Intestinal dysfunctions, particularly those involving TLRs, IFNG, NFKB1, and TNF, have established pathogenic roles in several mouse models of colitis and in the onset of human IBD." (PMID 35732858, 2022). "Mice deficient in both TNF-α and IL-10 spontaneously develop severe colitis-associated colon cancer." (PMID 35954156, 2022). "This theory seems in line with the reports of reduced CRC risk after anti-TNF exposure in patients with long-standing colitis." (PMID 35884974, 2022). "The present findings show indeed that DSS-induced colitis was associated with a marked increase in inflammatory and apoptotic markers such as TNF-α, NFκB, and caspase-3." (PMID 34103031, 2021). "Treatment with Cardamonin reduces the secretion of IL-1β and TNF-α in patients with recurrent colitis and colitis-associated tumors and inhibits cell viability and the production of inflammatory cytokines in colorectal cancer cells in vitro." (PMID 34539403, 2021). "Induction of colitis by acetic acid caused significant increases in the level of TNF-α compared to the control group (p<0.001)." (PMID 34745922, 2021). "It is reported that Erysipelotrichaceae, Turicibacter and others are related to the elevation of TNF levels, IL levels in the Muc2 deficient mice with colitis." (PMID 34326769, 2021). "The secreted proinflammatory cytokines (IFN-γ, IL-2 and TNF-α) from immune cells result in loss of intestinal epithelial barrier integrity and magnify inflammatory response in colitis." (PMID 33808686, 2021). "Taken into account, TNF-α and IL-6 play an important role in body-weight loss induced by the secretion of neuropeptides, suppressing the appetite in colitis." (PMID 35052720, 2021). "In the CD45RBhi T cell transfer model of colitis, treatment with FAHF-2 decreased colitis progression as evidenced by decreased weight loss, histological inflammation and production of TNF-α, IFN-γ, IL-6, and IL-17 from the colon." (PMID 34926527, 2021). "When tested on an experimental model of colitis induced by dextran sulfate, oral fucCS attenuated the body weight loss, expression of colonic TNF-α gene and colon shortening caused by experimental colitis." (PMID 34436263, 2021). "TNF also mediates colitis caused by immune checkpoint blockade with anti–CTLA-4 and anti–PD-1 antibodies." (PMID 34101617, 2021). "After treatment with HMC, colitis improvement was associated with the rise in colon antioxidant status and the inhibition of pro-inflammatory cytokines IL-1β, IL-6, IL-33, and TNF-α in the colon." (PMID 33499333, 2021).
colitis (continued). "Another study to show TNF-α induction of heparanase (during colitis-associated tumorigenesis) proposed that since TNF-α also induced upregulation of EGR1 that TNF-α induced heparanase expression via activation of EGR1, although this is yet to be confirmed." (PMID 34681753, 2021). "The activation of the mitogen-activated protein kinase (MAPK) pathway and elevated expression of cytokine-encoding genes decreased in TNF-α-treated Caco-2 cells or DSS-induced colitis mice when treated with SOD3 or SOD3-MSCs." (PMID 34208517, 2021). "Previous researchers have shown that in the mouse dextran sulphate sodium (DSS)-induced colitis model, SIGNR3 deficiency can lead to exacerbated colitis, as well as an accompanying increase in TNF-alpha production." (PMID 34889727, 2021). "Surprisingly, TNFα inhibition can cause de novo disease or reactivation of inflammatory disease, such as psoriasis, arthritis, colitis, uveitis, etc.." (PMID 33540543, 2021). "The increased abundances of Candidatus Saccharimonas, and Roseburia in colitis are reportedly associated with reduced IL-17 and TNF-α expression." (PMID 34824318, 2021). "In this case report, we describe an adolescent male with X-linked CGD and steroid-refractory colitis with perirectal fistula and abscesses, who was initiated on treatment with infliximab, a TNF-α inhibitor." (PMID 34760850, 2021). "Together, these results suggest that P2RX1 antagonist can facilitate the efficiency of anti-TNF-α therapy in mouse colitis, and the mechanism is associated with decreased inflammatory cytokine and neutrophil infiltration." (PMID 34354708, 2021). "In a study using the DSS-induced colitis model, loss of miR-155 was found to ameliorate colitis by reducing TNF-α and interleukin- 6, -12 and -17 in the tissue." (PMID 33647883, 2021). "Abnormal intestinal immune response is one of the characteristics of UC, and TNF-α and IL-1β are pro-inflammatory mediators caused by the immune response of colitis." (PMID 34208038, 2021). "Development of colitis was associated with a 3- to 60-fold increase in mRNA expression levels of pro-inflammatory cytokines including IL-1β, tumor necrosis factor (TNF)-α, interferon (IFN)-γ, IL-17, and IL-22." (PMID 34299013, 2021). "ET treated mice had less severe colitis as evidenced by reduced weight loss, colonic inflammation, and production of inflammatory cytokines (TNF-α, IFN-γ, and IL-17A) from the colon." (PMID 33717186, 2021). "TNBS-induced colitis was accompanied by elevated colonic expression of genes encoding representative proinflammatory cytokines (TNF-α and IL-6) and enzymes (COX-2), which was suppressed by TauCl administration." (PMID 33803551, 2021). "Anti-inflammatory drugs including 5-aminosalicylic acid (5-ASA), thiopurines, and anti-tumor necrosis factor (TNF)-α used in the treatment of IBD have also reduced colitis-associated cancer and have been firmly established as chemo-preventive." (PMID 33316984, 2020). "Exposure to EC also induced colitis in mice, causing colon shortening and increased myeloperoxidase activity, TNF-α and IL-6 expression, NF-κB activation, and infiltration of NF-κB/CD11c+ cells (activated DCs and macrophages) in the colon." (PMID 32224881, 2020). "IS exposure-induced colitis caused colon shortening and increased myeloperoxidase activity, TNF-α and IL-6 expression, and NF-κB activation in the colon." (PMID 32224881, 2020). "This drug is already used more widely in ICI-related refractory colitis with good outcomes, suggesting that decreasing the pro-inflammatory state associated with TNF-α is useful in treating irAE." (PMID 33362680, 2020). "In colitic mice, the formulation significantly reduced TNF-α mRNA (50%) and protein (45%) expression and ameliorated colitis symptoms reflected by the DAI, loss of body weight, colon length, MPO activity and histopathology." (PMID 32545207, 2020).
colitis (continued). "In a dextran sodium sulphate caused mice colitis model, P. edulis peel flour reduced pro-inflammatory cytokine TNF-α, IL-1β, IL-6, IL-12, and IL-17 expression and decreased the expression of MCP-1 and ICAM-1." (PMID 32508631, 2020). "We also examined mice lacking Atg16l1 or A20 in intestinal epithelial cells (IECs) because these genes encode important negative regulators of TNF-induced cell death, and their mutation is associated with colitis in humans." (PMID 31101885, 2020). "Prophylactic anti-TNF antibody or TNF inhibitor (TNFR2–immunoglobulin G) can significantly reduce the increased colitis caused by double-checkpoint blockade." (PMID 32226426, 2020). "In TPH1 deficient colitis mice, the severity of colitis and the level of IL-1β, IL-6, and tumor necrosis factor (TNF)-α was clearly reduced, and reloading 5-HT increased the severity of DSS-induced colitis." (PMID 32117308, 2020). "L. acidophilus blocks the colitis-associated immune response of the IL-23/Th17 axis by downregulating the activity of IL-17, TNFα, IL-23, TGFβ1, and STAT336." (PMID 32123288, 2020). "Treatment efficacy was confirmed in all tested models, where systemically administered hBD2 mitigated inflammation, improved disease activity index, and hindered colitis-induced body weight loss on par with anti-TNF-α and steroids." (PMID 32076420, 2020). "We noted that, administration of S-EVs into the ileal loop of DSS-colitis mice significantly suppressed the mucosal inflammation-associated increase in TNF-α and IL-17A compared to that of control EVs (C-EVs)." (PMID 33182773, 2020). "Surprisingly, we found that Ct55-deficient mice were resistant to colitis-associated tumorigenesis in the animal AOM/DSS model by targeting TNF-α-induced NF-κB signaling." (PMID 30944312, 2019). "It is well recognized that the activation of the TNF pathway leads to the activation of NF-κB signaling, and many studies have shown that NF-κB signaling plays a crucial role in colitis-associated colorectal cancer." (PMID 30944312, 2019). "Beside these human studies, in a murine study a role for TNFα signalling during colitis-associated tumour development was suggested, since elevated levels of TNFα were found during colon carcinogenesis induced by AOM/DSS." (PMID 30995806, 2019). "The relative abundance of the Actinobacteria phylum was positively associated with both ileal CD and colitis phenotype and negatively associated with detection of C. difficile fecal toxin and anti-TNFα biologic use within 8 weeks of surgery." (PMID 30818349, 2019). "RNA-seq analysis and western blotting showed that Ct55 deficiency played a protective role in colitis-associated colorectal cancer by regulating TNF-α-induced NF-κB signaling." (PMID 30944312, 2019). "Dizocilpine, particularly with intermediate dose of 1mg/kg significantly improved animal’s weight loss as well as macroscopic and microscopic signs of colitis, reduced colonic levels of IL-1β, IL-6, TNF-α and MPO activity." (PMID 32641944, 2019). "Meanwhile, iGMSCs were not able to induce as effective reductions of serum levels of TNF-α and IL-17 in colitis mice as did the GMSCs, assessed by enzyme-linked immunosorbent assay (ELISA)." (PMID 31796122, 2019). "These newly recruited cells, described as F4/80int CX3CR1int, become the dominant subset and support key pathogenic mechanisms in colitis through robust expression of TNFα and IL-23 and efficient activation of T cells through MHCII." (PMID 31710624, 2019). "This exaggerated IEC apoptosis is reported to be due to increased susceptibility to TNF-α and, as expected, TNF-α inhibition reduces the colitis severity in Atg16L1 conditionally KO mice." (PMID 30764829, 2019). "Development of colitis is often associated with chronic inflammation, characterized by inflammatory cellular infiltration and series of cytokines secretion, such as TNF-α, IFN-γ, IL-6, IL-1β, IL-4, and IL-10." (PMID 29538417, 2018).
colitis (continued). "In contrast, adoptive transfer of iTreg cells reduces pathological scores and levels of TNF-α and IL-17 in colons of colitis mice, and IL-10-deficient mice spontaneously developed severe colitis." (PMID 30166541, 2018). "TNF-α and IL-6 signaling has been proposed as a tumor-promoting mechanism in colitis-associated cancer." (PMID 29636751, 2018). "Rats in the TNBS group developed symptoms of colitis, including: body weight loss, colon mass index increase and damage of intestinal tissues with concomitant increase in TNF-α, IL-17, MDA levels and decreased SOD activity." (PMID 28337639, 2018). "Increasing productions of proinflammatory cytokine are associated with DSS-induced colitis, which produce various proinflammatory cytokines, including TNF-α, IFN-γ, IL-6, IL-8, IL-12, and IL-17." (PMID 30402509, 2018). "Although initially, TNF-α was considered to serve as a tumor-suppressive factor, due to its conditional pro-apoptotic function, it was recently found to promote colitis-associated tumor development by linking inflammation and cancer." (PMID 28492497, 2017). "Here we have combined one of the best UC models currently available, namely Winnie and the TNFαKO mouse to generate a TNFα-deficient Winnie to study early onset colitis." (PMID 28796256, 2017). "In inflammation induced mouse models of CRC it was shown that IL-17A deficient mice showed milder colitis, fewer and smaller tumors and expressed reduced levels of IL-6 and TNF." (PMID 28881611, 2017). "Above all, TNF-α is a key risk factor within the NF-κB pathway to the development of colitis-associated CRC." (PMID 28852270, 2017). "In other studies, TNF-α deficiency was associated with severe colitis and cancer along with increased blood levels of IL-6, IFN-γ, and IL-17A." (PMID 28492497, 2017). "The results indicate that susceptibility to colonic inflammation is linked to a Th1 polarization in the immune system as especially evident from the induction of TNF-α and IFN-γ production." (PMID 28584821, 2017). "Tumor necrosis factor alpha (TNFα) is known to be a positive regulator of UC-associated colon cancer, and it is overexpressed in a murine model of carcinoma arising on colitis." (PMID 28621756, 2017). "Injection of anti-S100a9 Ab or infliximab (anti-TNFα Ab) during colitis induction significantly ameliorated body weight loss and DAI scores compared with that of injection of control IgG Ab." (PMID 29326691, 2017). "Enhanced expression of TNF-α was demonstrated in colitis-associated CRC mouse models that were established by combined treatment of AOM and DSS." (PMID 28852270, 2017). "TNF-α and IL-6 are both central proinflammatory cytokines associated with the development of intestinal inflammation in animal colitis models and human IBD." (PMID 28607633, 2017). "For example, in dextran sulfate sodium- (DSS-) induced colitis in mice, both oral and dietary administration of resveratrol caused reductions of proinflammatory cytokines, TNF-α, IFN-γ, IL-8, and IL-1β, and an increase of the anti-inflammatory cytokine IL-10." (PMID 28465680, 2017). "Here we found that CD11b deficient (Itgam−/−) mice were more susceptible to dextran sulfate sodium (DSS)-induced colitis, with more tumor necrosis factor α (TNF-α) while less IL-10 production." (PMID 27188220, 2016). "IL-1β, IL-6 and TNF-α are all implicated in increasing the severity and duration of colitis in both mouse models and human patients." (PMID 26998523, 2016). "Many of the inflammatory cytokines attenuated by FFAR2 and FFAR3, including C5, CCL1, CCL2, GM-CSF, IL-1α, IL-1β, ICAM-1 and TNF, are associated with colitis." (PMID 27667443, 2016). "Rifaximin administered alone caused a partial decrease in the level of IL-1β and TNF-α in colonic mucosa of animals with colitis." (PMID 27433160, 2016). "A recent report demonstrated that TRAF-2 deficient mice spontaneously developed severe colitis due to enhanced TNFα-induced apoptosis of colonic epithelial cells." (PMID 27997590, 2016).